KRAS (KRas proto-oncogene, GTPase)
Diseases named in the same sentence as KRAS in open-access papers (continued):
Sharing a sentence is not in itself a finding about the gene and the disease.
tumor (continued). "Taken together, the data indicated that the application of both the gene-cutting CRISPR/Cas9 and mRNA-regulating dCas9-KRAB systems could lead to KRAS G12S protein downregulation in vivo and result in a strong anti-tumor efficacy." (PMID 32308773, 2020). "However, expression of both pan-RAS and KRAS degraders in mutant KRAS H358 xenografts induced regression of tumours after only 3 days of doxycycline treatment with a substantial regression of all tumours after 20 days of treatment." (PMID 32591521, 2020). "As NOTCH signalling plays an important role in KRas‐induced tumour formation in the lung, loss of USP28 reduced overall tumour burden and, while blocking SCC formation, also reduced ADC tumour burden in the lung." (PMID 32128997, 2020). "For example, information on clinical features (e.g., ECOG performance status, KRAS/BRAF mutation, primary tumor location) and therapeutic regimens (e.g., FOLFIRI, FOLFOX) given in combination with biological therapy were not available in administrative databases." (PMID 32244478, 2020). "Molecular aberrations involving various driver mutations including ALK, ROS1, KRAS, IDH1/2 and JAK2 may impact thrombotic risk in various tumor types." (PMID 32707653, 2020). "However, when KRAS mutation was assessed together with FDG uptake pattern, mean tumor SUVmax was observed to increase significantly in subjects with KRAS mutation." (PMID 32079384, 2020). "KRAS and KDM6A mutations were detected in tumor samples collected from each patient." (PMID 32466769, 2020). "Therefore, there is a possibility of improving the outcome of patients carrying KRAS and BRAF mutations by supplementing chemotherapy with ascorbate to maximize the oxidative stress in tumor cells." (PMID 32605263, 2020). "This study advocates that LC/SRM and IMS/MS could both be used to identify single amino acid substitutions in KRAS as an alternative to commonly used methods such as circulating tumour DNA analysis." (PMID 31800120, 2020). "In our cohort, 28 of 83 (34%) patients had BRAF V600Mx, KRAS Mx, NRAS G12/G13 and/or NRAS Q61 mutations in their bone marrow tumor DNA sample (4 [5%] BRAF V600Mx mutations, 13 [16%] KRAS Mx mutations, 3 [4%] NRAS G12/G13 mutations, 14 [17%] NRAS Q61 mutations)." (PMID 32284750, 2020). "Our findings are in line with this research, and we suggest that RhoA may acts as a tumor suppressor in KRAS induced NSCLC." (PMID 32244355, 2020). "Given the significant oncogenic function of KRAS, drugs targeting KRAS may provide a promising selection for tumor therapy." (PMID 33254149, 2020). "We did not observe significant association between KRAS genotype and lipid profile or tumour location." (PMID 32594310, 2020). "A putative relation between EGFR/KRAS mutation and the promoter methylation of CDH1, CDKN2Ap16, RASSF1A, TERT, and WT1 could influence tumor progression and therapy response." (PMID 32605217, 2020). "KRAS is important in promoting cell survival and growth in tumor cells." (PMID 32206449, 2020). "In an attempt to improve the understanding of immune activity in molecular subgroups of CRC, we analysed the distribution of different immune cell subsets in relation to tumour MSI/MSS status, CMS subtype, as well as BRAF and KRAS mutation status, and identified several significant relations." (PMID 33228141, 2020). "Additionally, molecular tumor characteristics, such as microsatellite instability, CpG island methylator phenotype (CIMP), and mutations in KRAS and BRAF, were evaluated in our CRC study population." (PMID 30786938, 2019). "Notably, MYC, SUZ12, and KRAS can also be suppressed by 5‐Aza in other manners, especially with the involvement of miRNAs in different tumor microenvironments." (PMID 30791232, 2019). "The location of primary tumor (left vs. right sided) and KRAS and BRAF mutation status did not significantly impact on mOS." (PMID 31615124, 2019).
tumor (continued). "We identify a previously unknown context-dependent tumor-supporting function of ARID1A in CRC downstream of KRAS signaling." (PMID 31217031, 2019). "Poloppin led to cell death in KRAS mutant cancer cells in vitro and decreased tumor size in vivo." (PMID 31040125, 2019). "Elevated VEGF mRNA levels were detected in tumor cell lines expressing mutant KRAS." (PMID 31600989, 2019). "To test whether GLI2 induction is required to sustain growth of tumor cells following suppression of KRAS*, we stably overexpressed Flag-tagged mouse GLI2 in iKRAS cell lines (iKRAS-GLI2) prior to Dox withdrawal." (PMID 31134896, 2019). "This increase could be associated with the mitochondrial fatty acid beta oxidation to respond to the increasing energy demand triggered by KRAS G12C to fuel cell or tumor growth and proliferation." (PMID 31681616, 2019). "Subsequent comparisons of genomic profiles from an additional twelve LGSC cell models showed frequent deletion of Chr9p (including loss of MTAP and CDKN2A genes) and oncogenic mutations in KRAS and NRAS genes, in agreement with results from previous studies on LGSC tumor tissues." (PMID 30636931, 2019). "Indeed, whereas 97% of tumours carried mutant KRAS, 18% of the CTCs were found to carry only the KRAS wild type allele." (PMID 31248203, 2019). "Notably, wild-type KRAS is found in tumors where NRP1 has tumor-promoting properties, while in tumors where NRP1 acts as a tumor suppressor, oncogenic KRAS mutations are found." (PMID 30717262, 2019). "For prognostication, pre- and posttherapeutic analyses alike of KRAS and APC mutations provided information on tumor load (quantitative analysis) and allowed molecular profiling (qualitative analysis) to guide treatment decisions by determining the indication for (neo-)adjuvant therapies." (PMID 32328554, 2019). "Treatment of the KRAS-mutant mixed cultures with cetuximab or trametinib alone reduced tumor take rate (determined on day 38 post-injection) and substantially prolonged the period required for achieving an equal 1.0 cm3 tumor mass in two out of three tumors." (PMID 30925167, 2019). "Recent studies suggest that Kirsten Rat Sarcoma Viral Oncogene Homolog (KRAS) activation and downstream signalling can impact on the properties and functions of the tumour microenvironment, and thus may influence histological phenotype." (PMID 31111275, 2019). "To test whether the use of dual miR-21 and KRAS targeting using RNA-based therapy can disrupt tumor maintenance, we tested our combo-therapy in vivo." (PMID 31523393, 2019). "Nevertheless, since the oncogenic KRAS point mutation is a frequent event during PDAC, the identification of this mutation in tumour tissues may aid diagnosis." (PMID 31248203, 2019). "Evaluation of the tumor growth volumes of each mouse throughout the treatment highlighted some dramatic changes in tumor growth behavior in the group receiving the combination of anti-miR-21 and siRNA anti-KRAS." (PMID 31523393, 2019). "Inflammatory features like PD-L1 expression may be affected by traditional stratifying criteria (i.e. gender, age, smoking status, histology, tumor stage or KRAS/EGFR status)." (PMID 31125352, 2019). "For example, a KRAS mutant tumor cell still expresses wild-type NRAS and HRAS proteins." (PMID 31878223, 2019). "Even CTCs from five out of the 12 metastatic tumours were KRAS WT (Wild Type)." (PMID 31248203, 2019). "Enrolled in the OncoTrack study with an adenocarcinoma of the colon and synchronous liver metastasis, the KRAS G12C variant detected in the primary tumor was not displayed in the corresponding cfDNA from patient 374‐CB‐M." (PMID 31134762, 2019). "The efficiency of KRAS knockdown in tumours was confirmed by IHC." (PMID 30833665, 2019). "In conclusion, we provide the first evidence that miR-873 acts as a tumor suppressor by targeting KRAS and that miR-873-based gene therapy may be a therapeutic strategy in PDAC and TNBC." (PMID 30654191, 2019).
tumor (continued). "Seven patients from the group of 19 NSCLC subjects who donated blood and EBC samples had no detectable KRAS mutation in all analyzed tumor samples." (PMID 30368666, 2019). "As such, STAT3 is an attractive target for KRAS mutant tumor treatment." (PMID 31484165, 2019). "Six out of 23 (26%) patients had a tumour pair with one KRAS mutant and one wild type tumour." (PMID 30894686, 2019). "The cancer genome screening of the fresh frozen tumor of the palate mucosa was performed using Oncomine® Cancer Research Panel (OCP, Thermo Fisher Scientific, MA, USA), which successfully identified an oncogenic KRAS mutation at codon 12 (p.G12D)." (PMID 30634950, 2019). "KRAS-mutant tumor cells appear to rely on KRAS for cell proliferation." (PMID 30935067, 2019). "Thus, by blocking IL-6, the lung tumor microenvironment can be reprogrammed to limit tumor development and progression in KRAS tumors." (PMID 31652660, 2019). "Further, persistent downstream signaling through the RAS axis due to KRAS mutations can activate multiple processes involved in tumor progression and metastasis without the influence of EGFR and other cell surface receptor kinases." (PMID 31771279, 2019). "Oncogenic KRAS plays a vital role in controlling tumor metabolism by enhancing aerobic glycolysis." (PMID 30819189, 2019). "KRAS G12 was the most concordant hotspot (8/31) in all tumor types." (PMID 31546879, 2019). "And high expression of eIF3E and eIF3J was observed more in patients with residual tumours (13/4 vs. 172/170, p = 0.0456) and without mutations in KRAS/EGFR/ALK (47/48 vs. 86/46, p = 0.0206), respectively." (PMID 31885740, 2019). "As we recently reported, KM2 tumours sporadically progress to a higher-grade disease characterized by increased morphologic heterogeneity and sharply increased phosphorylation of Erk1/2, downstream of KRAS." (PMID 31032816, 2019). "STK11 inactivation leads to the an increased infiltrate of protumoral neutrophils, a decrease of tumor-infiltrating cells and reduced PD1 and PD-L1 expressions in the tumor microenvironment, both in a KRAS-driven mouse model of lung adenocarcinoma and in cell lines." (PMID 31172347, 2019). "Interestingly, the top predictions from genomic data across tumor types were all MEK inhibitors (PD0325901, selumetinib, and trametinib), which were associated with BRAF and KRAS/NRAS mutations." (PMID 31253656, 2019). "Only one patient without baseline mutations in ctDNA nor tumor tissue gained mutations in KRAS, NRAS, and BRAF at progression in ctDNA." (PMID 31350822, 2019). "Second, we did not study KRAS-mutant patients for co-occurring mutations in additional tumor-associated pathways." (PMID 31600989, 2019). "APC and KRAS are the most frequent mutations encountered in CRC and our model can express both the mutation simultaneously along with definitive development of neoplasm." (PMID 31766149, 2019). "Results of cell culture models assessing the transformation capacity of different RAS-mutant tumor cells indicated that SOS2 inhibition may emerge as a therapeutic option in KRAS-mutant cancers." (PMID 31261735, 2019). "Additional factors considered in the adjustment model, comprising tumor colorectal subsite location, smoking history, BMI, and mutations of KRAS, NRAS, BRAF, and PIK3CA, did not meet the 10% change in coefficient criteria for confounder selection." (PMID 31367996, 2019). "Since concomitant KRAS and BRAF tumor mutations are considered mutually exclusive we wanted to confirm that the CRC cases carrying KRAS mutation show negative BRAF V600E staining by IHC with anti-BRAF V600E (VE1) antibody." (PMID 29127628, 2019). "Pancreatic juice from PDAC patients is rich in KRAS mutations often not seen in the primary tumor and possibly reflecting precancerous lesions in other regions of the pancreas." (PMID 30611220, 2019). "Knockdown by siRNA of either WDSOF1 or HBS1L was synthetic lethal in a KRAS-driven tumor model." (PMID 31660150, 2019).
tumor (continued). "ErbB2 overexpression and KRAS oncogenic mutations also contribute to the selective HK2 induction in tumor tissues, though the mediating machinery is not completely understood." (PMID 31201299, 2019). "Here, we demonstrate that CD4+ T cells when incubated with tumor-derived exosomes from mutant (MT) KRAS non-small-cell lung cancer (NSCLC) cells, patient sera, or a mouse xenograft model, induce phenotypic conversion to FOXP3+ Treg-like cells that are immune-suppressive." (PMID 31635338, 2019). "In addition, after dual targeting of miR-21 and KRAS (combo), the final tumor growth was reduced by 43.4%, revealing an additional 6% anti-tumor effect." (PMID 31523393, 2019). "In addition, the correlation between KRAS MAFs in ctDNA and tumor tissue was poor (p = 0.007, r2 = 0.200)." (PMID 31850201, 2019). "Despite being promising, oncogenic KRAS codependencies may vary between tumor types, according to the genetic background of the cell lines used and the KRAS mutation, limiting the capacity to validate the findings amongst different studies." (PMID 31847096, 2019). "Finally, when HC11 cells with CRISPR-deleted FASN were infected with PyMT or KRAS and grafted into wild-type animals, a delay on tumor onset was observed compared with wild-type counterparts." (PMID 31676791, 2019). "In particularly, STK11 mutations, inactivated in 20 to 30% of adenocarcinomas, and often associated with KRAS mutations, are associated with non-inflamed tumor microenvironment in a murine model." (PMID 31172347, 2019). "Furthermore, treatment with a class I PI3K inhibitor was able to block tumor growth in KRAS-driven PDAC." (PMID 30759745, 2019). "miR-27a was identified as a tumor suppressor in CRC, and it may directly target KRAS or EGFR to inhibit tumor cell growth." (PMID 31717759, 2019). "We also observed subclonal copy gain of KRAS in all 8 samples, as well as subclonal copy loss of both ELOVL2 and IRF4, all of which have been identified in tumours although the effect of these copy number losses in AML is unknown." (PMID 31645898, 2019). "Another evidence of loss of antigen presenting machinery leading to acquired resistance to cancer immunotherapy is provided identifying a polyclonal CD8+ T cell response against KRAS G12D in tumor-infiltrating lymphocytes obtained from a patient with metastatic colorectal cancer." (PMID 35582274, 2019). "However, the MAF of KRAS in ctDNA was significantly different from that in tumor tissue of the same person (p < 0.001)." (PMID 31850201, 2019). "Moreover, higher PDE6D expression correlated with enhanced tumor grading, tumor stages, and KRAS expression levels." (PMID 30901922, 2019). "Consequently, our methods predict substantially fewer unseen variants in KRAS than in FAT1, while the corresponding estimate of the probability of observing at least one new variant in a new tumor is noticeably higher for FAT1 as compared to KRAS." (PMID 31796730, 2019). "In conclusion, our study showed that KRAS MAF in ctDNA differed from that in tumor tissue in PC." (PMID 31850201, 2019). "Testing of DNA from a single primary tumor tissue block may wrongly assign KRAS WT status in 8–11.6% of patients." (PMID 31222012, 2019).
tumor (continued). "To further examine whether TNTs contribute to KRAS heterogeneity between cells by redistributing mutant KRAS to wild-type KRAS tumor cells, we co-cultured HCT-8 cells transfected with mutant KRAS and non-transfected HCT-8 cells." (PMID 31247990, 2019). "Furthermore, according to immunohistochemical staining, the levels of positive KRAS protein expression were lower in the tumor tissues from the co‐treated group than in the mock and control groups." (PMID 30347501, 2019). "In fact, activating mutations in KRAS and BRAF were already detected in tumor-initiating cells." (PMID 31614493, 2019). "Our findings suggested that immunogenic driver mutations, including KRAS-G12D, KRAS-G12R, KRAS-G13D, NRAS-Q61R, PIK3CA-H1047R, and C-Kit-D816V, have the potential to be promising off-the-shelf tumor immunotherapy targets in patients with the corresponding mutations." (PMID 30813491, 2019). "No BRAF or KRAS mutation was detected in cfDNA from patients with wild‐type tumor tissue, resulting in 100% assay specificity among all four cancer stages." (PMID 31134762, 2019). "Herein, we employed this peptide-based nanocarrier, “p5RHH”, for the delivery of siRNA against KRAS, and assessed its propensity to: undergo cellular uptake, transmit siRNA, regulate gene expression, effect cellular viability, and alter tumor growth for KRAS-driven tumors." (PMID 31413817, 2019). "Our analysis of patients’ baseline ctDNA revealed three additional patients who had KRAS mutations (KRAS p.G12A, p.G61H, and a combination of the two) that had not been detected in tumor tissue." (PMID 31350822, 2019). "In this study, we analyzed the sensitivity rates of KRAS mutation in ctDNA and tumor tissue for PC prediction and found that neither was satisfactory." (PMID 31850201, 2019). "Moreover, loss of both the KRAS and PTEN oncogenes promotes marked activation of NF-κB and its cytokine network, which is accompanied by infiltration of immune cells with known tumor-promoting properties." (PMID 31831007, 2019). "Primary tumor tissue obtained from colonoscopy was detected to be KRAS, NRAS, and BRAF wild type." (PMID 31852167, 2019). "When we explored whether the KRAS mutations identified in the CRC tumor tissue samples were consistently detected in the plasma cfDNA of the three CRC patients by dPCR, all three KRAS mutations were consistently identified." (PMID 31896242, 2019). "Additionally, the expression levels of both SUZ12 and KRAS were pronouncedly higher in metastatic tissues than in primary tumor tissues, suggesting the functions of SUZ12 and KRAS were also closely metastasis related." (PMID 30791232, 2019). "Therefore, we constructed a cell line panel from these three tumour types and then employed KRAS mRNA knockdown as a measure of productive ASO uptake capacity across these cancer cells." (PMID 30927008, 2019). "We may also argue that identification of the KRAS mutation, which is detected very early during PDAC oncogenesis, may help detect early disease, which is eligible for surgery, before tumours grow too big or even disseminate." (PMID 31248203, 2019). "While these results are promising, it does not explain differences in tumor response to cetuximab in the majority of HNSCC patients lacking the KRAS variant." (PMID 31346466, 2019). "In the present study, among patients with non-metastatic CRC bearing tumor-associated KRAS mutations, we were able to detect KRAS mutations in ctDNA after enrichment assay of CEA-negative patients." (PMID 31383871, 2019). "Utilization of iRGD TPNs carrying KRAS siRNA also led to the limiting of tumor growth in vivo." (PMID 31523393, 2019).